CD5 (CD5 molecule)
Diseases named in the same sentence as CD5 in open-access papers (continued):
Sharing a sentence is not in itself a finding about the gene and the disease.
tumor (continued). "The density of cells staining positive for the T‐cell markers CD3 and CD5 decreased in all tumor regions with increasing age [CD3: tumor centre (P = 0.007), invasive front (P = 0.019) and whole tumor (P = 0.005); CD5: tumor centre (P = 0.022), invasive front (P = 0.006) and whole tumor (P = 0.006)]." (PMID 33024560, 2020). "CD5 was validated as a tumor target antigen in clinical trials using toxin-conjugated CD5 mAbs." (PMID 33081391, 2020). "However, the correlation between CD5 level expression and T cell activation and effector function in the tumor microenvironment and in peripheral organs is ill-defined and requires further investigation." (PMID 33584650, 2020). "Therefore, in situ adaptation (down-regulation) of CD5 expression in tumor-infiltrating lymphocytes has been shown to elicit strong anti-tumor reactivity in lung carcinoma patients." (PMID 33287301, 2020). "Initially, we studied 233 patients with tumour purity derived from CD5/CD19 flow cytometry." (PMID 32015491, 2020). "The increased level of CD5 on T cells upon TCR/CD3 stimulation by monoclonal antibody treatment or by exposure to poorly immunogenic 4T1 tumor antigen reported here suggests that CD5 level may be directly increased by that activation." (PMID 33584650, 2020). "Furthermore, CD5 has been reported to protect tumor-reactive circulating T cells from activation-induced cell death (AICD) following recognition of autologous tumor." (PMID 33584650, 2020). "On the other hand, higher CD5 expression is associated with better prognosis in non-small cell lung cancer, probably due to increased resistance to activation-induced cell death (AICD) of high-affinity tumor-specific T lymphocytes." (PMID 33287301, 2020). "CD5-/- DC are more potent than WT DC in the induction of anti-tumor immunity and CHS responses." (PMID 31491023, 2019). "Consequently, CD5-/- DC were significantly more potent than wild type DC in the induction of anti-tumor immunity and contact hypersensitivity responses in mice." (PMID 31491023, 2019). "Both EBV‐harboring and PD‐L1 expression on tumor cells, but not CD5, were associated with worse overall survival (OS) in iDLBCL patients receiving rituximab‐containing chemotherapy (P = 0.0354, P = 0.0092, and P = 0.1097, respectively)." (PMID 30449068, 2018). "Furthermore, high NLRs have also been associated with infiltration of tumor by lymphocytes with low CD3+ and high CD5+ expression." (PMID 29945635, 2018). "Antitumor activity of tumor-infiltrating lymphocytes (TIL) is inversely related to CD5 expression." (PMID 29701673, 2018). "In vivo BrdU incorporation assays and Annexin V staining revealed a several fold increased proliferation and apoptosis rate of CD19+CD5+ CLL cells from TCL1 Nfat2−/− mice as compared to TCL1 mice with intact NFAT2 expression demonstrating a highly accelerated tumour cell turnover." (PMID 28970470, 2017). "CD5 is felt to regulate antitumor immune response by potentiating tumor-specific T-cell reactivity." (PMID 28099461, 2017). "Recent evidence shows that the lymphocyte receptor CD5 –a negative regulator of TCR-mediated signaling- may play a role in the anti-tumor immune response." (PMID 29296231, 2017). "Interestingly, SSBP2 expression abolished the prognostic significance of CD5 expression, suggesting a tumor-suppressor role of SSBP2 for CD5 signaling." (PMID 25760242, 2015). "Bcl-2 inhibitors, STAT3 inhibitors, and therapeutic strategies modulating BCR signaling, tumor microenvironment and cytokine/chemokine axes may help in the management of CD5+ DLBCL patients." (PMID 25760242, 2015). "Additionally, they were able to show that these CD5 CAR T cells had tumor suppression capabilities when co-cultured for longer periods of time with these CD5+ cell lines." (PMID 26484338, 2015).
tumor (continued). "More interesting from a future therapeutic perspective, 200-μM PKHB1 treatment for 2 h killed the CD5+ tumor B cells (~50% of Annexin-V-positive/PI-positive cells) while sparing the residual CD5− B lymphocytes and T cells of the CLL patients (~5% and ~10% cytotoxicity, respectively)." (PMID 25734483, 2015). "In this scenario, down-regulation of CD5 could also be advantageous for tumour infiltrating lymphocytes." (PMID 25237383, 2014). "However, it is notable that all the explanted tumor cell lines had upregulated expression of CD5 and expressed higher levels of MHC II than the parent cell lines." (PMID 21931547, 2011). "Interestingly, the combined injection of anti-CD5 with anti-HLA-DR or with anti-CD71 led to longer mouse survival, as compared to single mAb injection, up to complete inhibition of tumour growth in 100% mice treated with both anti-HLA-DR and anti-CD5." (PMID 21504579, 2011). "We propose that CD20+CD5+sIgM+ lymphocytes producing anti-carbohydrate antibodies with anti-tumor activity, might contribute to the response to imatinib treatment." (PMID 21533122, 2011). "Furthermore, we characterized the rather mild inflammatory infiltrate, which showed increased T-lymphocytes (CD5/CD3 positive) near the invasion front of the tumor, whereas centrally in the tumor only few T-lymphocytes could be found." (PMID 39886672, 2024). "Furthermore, tumour growth was delayed in mice treated with anti-CD5 MAb." (PMID 38487537, 2024). "Together, this evidence suggests that CD5 may be a potential immunotherapeutic target for antibody blockade to increase T cell activation and allow T cells a better metabolic advantage in a glucose-depleted tumor microenvironment." (PMID 35327505, 2022). "Tumor cells were enlarged with large edematous nuclei and significant infiltration of lymphocytes, and immunostaining showed that the tumor cells were bcl-, CD5-, and p40-positive, and the lymphocytes were CD3-positive and CD99-negative, leading to the diagnosis of TLEC." (PMID 34638279, 2021). "Additionally, CD5 is not expressed on hematopoietic stem cells and other non-hematopoietic cells, minimizing the risk of off-tumor effects." (PMID 33410096, 2021). "Successfully engrafted mice with comparable disease load (percent CD19+/CD5+ B cells in the blood) were randomly assigned to receive ibrutinib or vehicle by daily oral gavage at any given enrollment time to control for different growth kinetics of the engrafted tumor cells." (PMID 34732719, 2021). "We also determined whether CD5 levels on T cells were affected by the presence of tumor homografts." (PMID 33584650, 2020). "The soluble form of CD5 (sCD5) can be found at low concentrations (pg/mL range) in the serum of healthy individuals, generated through proteolytic cleavage upon lymphocyte activation; sCD5 has been recently demonstrated to exert an immunomodulatory effects on experimental tumor models." (PMID 32906648, 2020). "Furthermore, a fraction of both CD4+ T cell and CD8+ T cells recruited to the tumor microenvironment have lower CD5 levels than T cells in lymph and spleen, either because CD5 is downregulated by the tumor microenvironment or T cells with lower CD5 are preferentially infiltrated into tumors." (PMID 33584650, 2020). "However, a future study with larger numbers of cases may determine that the CD5 low T‐cell group encompasses a mixture of neoplasms." (PMID 31693230, 2020). "However, we report here for the first time that CD5 levels in these subsets is different in lymphoid organs and the tumor microenvironment and that CD5-/low TILs exhibit increased markers of activation and effector function, unlike CD5low T cells in lymphoid organs." (PMID 33584650, 2020).
tumor (continued). "Tumor growth was monitored once a week by measuring the percentage of CD5 + /CD7 + tumor cells in the peripheral blood and by in vivo imaging to detect luciferase-expressing cells; for ethical reasons, mice were sacrificed when circulating CD5 + /CD7 + cells reached 40% of the total PBMC population." (PMID 30069011, 2018). "However, only one previously reported case of thymic MEC showed tumor cells were positive to CD5." (PMID 24444077, 2014). "Tumor cells expressed T-cell markers (CD2, CD3, CD5, CD7; heterogeneous) and cytotoxic markers (TIA-1) and showed CD30 and CD56 positivity, with EBV positivity confirmed by EBER in situ hybridization." (PMID 41744967, 2026). "The use of six specific IHC markers—CD20, CD5, CD8, CD68, CD23, and CD45—is based on their established roles in lymphocyte differentiation, tumor microenvironment characterization, and specific disease pathologies relevant to the study's focus." (PMID 40134445, 2025). "Twelve studies were on T cell malignancies; they KO CD2, CD3, CD5, or CD7 and simultaneously targeted these antigens on tumor cells." (PMID 41354926, 2025). "Immunophenotypically, the tumor cells exhibit a mature germinal center B-cell profile, with positivity for CD19, CD20, CD79α, PAX5, CD10, and BCL6, and negativity for CD5 and TdT." (PMID 41561748, 2025). "Laparotomy revealed a transmural tumor mass, and histopathological and immunohistochemical analyses confirmed EATL (CD3+/CD103+/TIA-1+/GRANB+, CD5-/CD8-, Ki-67 ~70%)." (PMID 41357592, 2025). "Immunohistochemical examination showed expression by the tumor cells of antibodies to CD20, CD5, Bcl2, and cyclin D1." (PMID 38698463, 2024). "Immunohistochemical staining of the tumor cells was positive for CD3, CD5, CD7, CD8, granzyme B, and TIA." (PMID 38404589, 2024). "Treatment with anti-CD5 MAb resulted in an increased fraction of CD8+ T cells compared to CD4+ T cell in draining lymph nodes and the tumour microenvironment." (PMID 38487537, 2024). "The depletion of CD5 in DCs affected the expression of CD5 on CD4+ and CD8+ T cells, which affected tumor elimination in response to ICB therapy." (PMID 38261139, 2024). "Flow cytometry was performed to confirm the MS results on several critical markers of tumor immune responses including CD25 (IL2RA), CD5, CD137 (TNFRSF9), ICOS, PD1 (PDCD1), CTLA4, and CD62L (SELL)." (PMID 38242867, 2024). "Histopathological examination of liver tissues obtained from HCC/NRASG12V mice revealed abundant immune infiltration in the tumor tissue and the presence of CD19+, CD5+, and CD1d+ cells." (PMID 39611128, 2024). "The activity of CIKs can be redirected towards tumor targets by the combination with bispecific antibodies (BsAbs) simultaneously targeting a CIK surface antigen (e.g., CD5 or CD3) along with a tumor antigen, such as the T-cell engager CD3xCD19 blinatumomab." (PMID 39311376, 2024). "Lymph nodes typically show a monomorphic infiltration of atypical cells, in which tumor cells express CD3 and CD2 and lack CD5 and CD4." (PMID 38892108, 2024). "This is because RFA therapy can inhibit the anti-tumor immune response by declining the population of T cells, inhibiting the activation of T cells and downregulating the expression of CD161 and CD5 in various T cell subpopulations." (PMID 38348038, 2024). "Tumor cells in MEITL are typically CD3+, CD5−, CD7+, CD4−, TIA-1+, granzyme B+, perforin+, and CD103+." (PMID 39447336, 2024). "The analysis of two independent cohorts of CLL B cells and PBMCs from a total of 97 patients demonstrated that CD5+CD19+CD27+ memory CLL B cells produce and secrete IL10 and TGFβ1, as part of the tumour cell secretome." (PMID 36973425, 2023). "According to the WHO definition, CLL/SLL cells typically co-express CD5 and CD23, and flow cytometry reveals that tumor cells express dim surface IgM/IgD, CD20, CD22, CD5, CD19, CD79a, CD23, CD43, and CD11c (weak)." (PMID 38258066, 2023).
tumor (continued). "Thus, CD5+ B cells might recognize tumors through increased avidity of IgM antibodies for overexpressed proteins or aberrant glycosylation patterns leading to structural differences in tumor proteins." (PMID 37965337, 2023). "In one single patient study, CD5 CAR-T cells were modified to secrete IL-15/IL-15 sushi complex, as IL-15 has been shown to strengthen the anti-tumor response." (PMID 37108359, 2023). "Some clinical trials reported tumor cells depletion in patients with T-ALL and cutaneous T-cell lymphoma after treatment with toxin-conjugated anti-CD5 mAbs." (PMID 36624522, 2023). "Tumor cells are positive for CD30, also known as Ki-1 antigen, and some of the T-cells markers, such as CD3, CD5 and CD43." (PMID 36975591, 2023). "In our previous study, we optimized the production of anti-CD5 CAR-T cells, which demonstrated rapid and potent cytotoxicity against CD5-expressing tumor cell lines." (PMID 38143760, 2023). "The M-MDSC were upregulated in patients (p < 0.0001) and were correlated with CLL tumor progression, poor prognosis, and correlated with the presence of CD4+ T and CD5+CD19+ cells." (PMID 36304465, 2022). "TILs such as CD3, CD4, CD5, and CD8, which attack cancer cells directly or contribute to antigen presentation, prevent tumor development in carcinogenesis." (PMID 36514573, 2022). "Degranulation was a prerequisite for perforin-granzyme-mediated tumor-killing of CAR-T cells, CD5/CD7 bispecific CAR-T cells upregulated CD107a expression after co-incubated with Jurkat, CCRF-CEM, MOLT-4, SUP-T1, CCRF-CD5KO cells, and CCRF-CD7KO cells." (PMID 35332132, 2022). "Dendritic cells that lack CD5 expression have also been shown to enhance CD4+ and CD8+ T cell activation and produce better anti-tumor responses." (PMID 35327505, 2022). "We observed that although CD3-CAR in the CAR-T-cell framework had higher in vitro activity than CD5-CAR, they were less active to reduce the tumor burden in a xenograft model, and this correlated with reduced CD3 cell surface levels after CAR treatment." (PMID 35158792, 2022). "The immunoreactivity of CD3, CD4, CD5, CD8, and PD-1 was analysed immunohistochemically in tumor-infiltrating lymphocytes (TILs) and stromal lymphocytes." (PMID 36514573, 2022). "Lymphocytes in the intra-epithelial compartment are described as having a phenotype that is similar to or consistently discordant with that of the invasive tumor and they must also express some pan-T-cell markers such as CD2, CD3, CD5, CD7." (PMID 36451465, 2022). "Despite this, the advantage of the CAR-NK framework was observed in vivo in both CD3 and CD5 CAR constructs, as CD3-CAR in a CAR-NK framework significantly reduced the tumor burden and CD5-CAR in a CAR-NK framework completely eliminated the tumor." (PMID 35158792, 2022). "Similar to EATL, tumor cells in MEITL are typically CD3+, CD5−, CD7+, CD4−, TIA-1+, granzyme B+, perforin+, and CD103+." (PMID 34830926, 2021). "The diagnosis of MCL was confirmed by the expression of CD20, CD5, cyclin D1, SOX11, and SAMHD1 of tumor cells." (PMID 34976810, 2021). "Immunohistochemistry (IHC) highlighted tumor cells as strongly positive for CD3, CD56, CD5, CD2, CD8, CD4, CD43, T-cell restricted intracellular antigen 1 (TIA-1) and granzyme B. The proliferation index, measured by Ki-67 expression was high with 60%." (PMID 33546043, 2021). "The strong negative correlation of MCP‐1 with global sTILs % was further substantiated by its inverse relationship with whole tumor density of CD3+, CD5+, CD8+ and FOXP3+ cells." (PMID 33024560, 2020). "However, in the tumor microenvironment, antigen presentation by tumor cells is less potent than presentation by professional antigen-presenting cells: under those circumstances, reduced CD5 levels could enhance TCR recognition to tumor epitopes and enhance T cell activation and anti-tumor activity." (PMID 33584650, 2020).
tumor (continued). "CD5 is induced based on the intensity of the TCR-MHC-1 interaction and poorly immunogenic tumor microenvironments that can lead to T cells with reduced CD5: a situation promoting increased TCR-MHC-I interaction and enhanced T cell activation." (PMID 33584650, 2020). "The B‐cell marker CD20 was less abundant in the invasive front (P = 0.042), and whole tumor (P = 0.031) in the older age groups, although the age effect appeared to be less pronounced than for the T‐cell markers CD3, CD5 and CD8." (PMID 33024560, 2020). "This study investigated a flow cytometric assay (CD160-ROR1FCA) targeting the tumor-specific antigens CD160 and receptor tyrosine kinase-like orphan receptor 1 (ROR1), along with CD2, CD5, CD19, CD45." (PMID 33344247, 2020). "It has been found that CD5+ Bregs inhibit tumor immune response by activating STAT3, thus promoting tumor development." (PMID 31662750, 2019). "Our data demonstrate that CD5-/- DC are more effective than WT DC in the induction of immune responses in tumor and CHS models indicating a regulatory role for CD5 in DC." (PMID 31491023, 2019). "Pleural carcinomatosis was strongly positive for CD5, CD117, and p63 as was the original tumor of the parotid, which allowed the diagnosis of a CASTLE tumor." (PMID 31475102, 2019). "We found that CD5 is commonly expressed on murine DC and has an inhibitory effect on the ability of DC to stimulate CD4 and CD8 T cells and to induce anti-tumor and contact hypersensitivity responses." (PMID 31491023, 2019). "In this study, we investigated the clinicopathological features of this disease to further understand the prognostic value of CD5, programmed cell death ligand 1 (PD‐L1), and Epstein‐Barr virus (EBV) on tumor cells." (PMID 30449068, 2018). "Tumor cells show expression of pan-B cell markers (CD19, CD20, and CD79a) and lack the expression of CD5, CD10 (a marker of germinal center B cells)." (PMID 29740389, 2018). "The tumor cells have a characteristic phenotype of TCR γ/δ+, βF1−, CD3+, CD2+, CD5−, and CD56+, with a strong expression of cytotoxic proteins." (PMID 29915722, 2018). "Tumor cells were commonly positive for TDT (21/26, 80.8%), CD3 (29/31, 93.5%), and CD7 (25/27, 92.6%), and they were variably positive for CD5 (16/24, 66.7%), CD99 (14/19, 73.7%), CD2 (12/18, 66.7%), and CD1a (13/21, 61.9%)." (PMID 28566711, 2017). "The expression of anaplastic lymphoma kinase (ALK), CD5, CD30, and C-Myc in tumor specimens from 109 patients was detected using IHC, and Epstein–Barr virus (EBV)-encoded RNAs (EBERs) were detected using fluorescence in situ hybridization." (PMID 29246182, 2017). "Because CD5 expression is commonly used as a marker for CLL, the presence of CD5low tumor B-cell populations would suggest that the “true” tumor load in patients is underestimated." (PMID 27693386, 2017). "To explore this possibility, we stained spleen cells from the BCL1 tumor-bearing mice with antibodies against BCL1-Id, and the cell surface markers, CD1d and CD5 that identify the B10 subset of Bregs." (PMID 27959896, 2016). "A panel of immunohistochemical stains was performed; the tumour was positive for p63, CD117, CKH, CD5, and CD3 in the lymphocytic part." (PMID 27110248, 2016). "Immunohistochemically, tumor cells are characterized by CD30, ALK, CD5, TIA-1, Granzyme B, EMA positive staining, and CD2, CD3, CD7, CD4, CD8, CD20, CD79a negative staining." (PMID 27612448, 2016). "Based on immunohistochemical staining, the phenotype of the tumor cells was CD3+, CD43+, CD56+, TIA-1+, CD30+, CD4-, CD5-, CD7-, CD8-, CD20- and CD79a-." (PMID 26126576, 2015). "Prognostic significance of CD5 expression in SSBP2+ and SSBP2− DLBCL patients also suggests a tumor-suppressor function of SSBP2 for CD5 signaling." (PMID 25760242, 2015). "Forexample, in patient 27, whose bone marrow had only one clonalDβ–Jβ rearrangement, the surface of the tumor cells did nothave CD3, CD5, CD4, or CD8, but only CD2 and CD7." (PMID 26483968, 2015).